HDAC6 (histone deacetylase 6)
Diseases named in the same sentence as HDAC6 in open-access papers (continued):
Sharing a sentence is not in itself a finding about the gene and the disease.
neurodegenerative disease (continued). "In various models of neurodegenerative diseases, pharmacological inhibition of HDAC6 restores alpha-tubulin acetylation and mitochondrial transport." (PMID 33374719, 2020). "HDAC6 has a role in influencing tau phosphorylation and autophagic flux in neurodegenerative disease." (PMID 32205467, 2020). "Histone deacetylase 6 (HDAC6) is a key enzyme in this neurodegenerative disease, in particular, as it relates to tau hyperphosphorylation." (PMID 29844403, 2018). "There are also studies demonstrating the effectivity of HDAC6 inhibitors in treating chronic diseases such as neurodegenerative diseases, cardiovascular diseases, and cystogenesis." (PMID 29179471, 2017). "The tubulin deacetylase HDAC6 is considered as a stress surveillance factor, is a key player in neurodegenerative diseases and a potential target for neuroprotection and regeneration." (PMID 29048427, 2017). "Rimming of pathological aggregate structures was reported in other neurodegenerative diseases, e.g., the rimming of huntingtin aggregates by p62 or HDAC6." (PMID 27481264, 2016). "Another specific HDAC6 inhibitor, tubastatin A revealed promising effects in neurodegenerative diseases but displayed apparently limited efficacy on solid cancer cells." (PMID 25759792, 2015). "Selective inhibitors of histone deacetylase 6 (HDAC6) show neuroprotective effects in neurodegenerative diseases and stimulate microtubule-dependent vesicular trafficking of BDNF-containing dense core vesicles." (PMID 24639629, 2014). "Selective inhibition of HDAC6 is thought to promote neuronal survival and regrowth after injury, offering a potential therapy for various neurodegenerative diseases." (PMID 24639629, 2014). "Overexpression of HDAC6 in a fly model of neurodegenerative disease indeed accelerates the degradation of the aggregate-prone protein by autophagy and protects the flies from neurotoxicity." (PMID 24312501, 2013). "Our new finding that TDP-43 mediates neurite outgrowth through HDAC6 provides a novel avenue to the understanding of neuronal signaling pathways contributing to neurodegenerative diseases." (PMID 21878116, 2011). "Moreover, HDAC6 is a promising target for neurodegenerative diseases due to its modulation of key proteins." (PMID 40284012, 2025). "In addition, HDAC6 inhibition can protect against neurotoxic insults in various neurodegenerative disease models." (PMID 36414713, 2024). "HDAC6 regulates the degradation of misfolded/aggregated proteins and the mitochondrial transport in hippocampal neurons, assuming an important role in neurodegenerative diseases." (PMID 37106761, 2023). "In addition, the aberrant activity of HDAC6 has been demonstrated in other neurodegenerative diseases such as Parkinson’s disease and Huntington’s disease." (PMID 37834214, 2023). "Nevertheless, the functions of HDAC6 in neurodegenerative diseases are controversial." (PMID 33282865, 2020). "To evaluate whether phospho-HDAC6 identified both intra- and extra-neuronal protein aggregates in neurodegenerative diseases, we analyzed AD human brains." (PMID 32655357, 2020). "HDAC6 is receiving increased attention as a therapeutic target for the neurodegenerative diseases." (PMID 29385079, 2018). "In neurodegenerative disease, HDAC6 may increase autophagy to protect neurons from an accumulation of misfolded protein caused by impairment of the ubiquitin-proteasome system." (PMID 27993690, 2017). "Therefore, our results suggest that modulation of Prx1 acetylation by HDAC6 inhibition has great therapeutic potential for AD and has further therapeutic possibilities for other neurodegenerative diseases as well." (PMID 28241840, 2017). "There has been an increased focus on HDAC6 in neurodegenerative disease." (PMID 21677773, 2011).
neurodegenerative disease (continued). "Further testing of brain-penetrant HDAC6 inhibitors, particularly those with improved metabolic stability, could provide additional validation of this therapeutic approach for AD, PD, and related neurodegenerative diseases." (PMID 41330635, 2026). "Therefore, through the process of drug repositioning, we hope to find molecules that will efficiently target HDAC6 but will not be associated with the mentioned drawbacks, thus offering new treatment approaches to neurodegenerative diseases." (PMID 39598445, 2024). "Likewise, histone deacetylase 6 (HDAC6), a protein involved with aggresome formation in neurodegenerative diseases, is also upregulated in prion infection and is suggested to increase autophagy through modulation of the PI3K-Akt-mTOR signaling pathway, resulting in neuronal protection against PrPSc." (PMID 33092231, 2020). "Therefore, our results suggest that targeting HDAC6 may represent a novel therapeutic intervention for neurodegenerative diseases with TDP-43 proteinopathy." (PMID 33282865, 2020). "Moreover, since disrupted ROS, Ca2+ homeostasis and axonal transport are common pathologies of neurodegenerative diseases, it is expected that HDAC6 inhibitor could also have therapeutic effects in other neurodegenerative diseases." (PMID 28241840, 2017). "Indeed, albeit HDAC2 and HDAC6 could represent promising drug targets in AD, it remains unknown which drug or dosing regime present the most efficacy, and similar conclusions can be drawn for other neurodegenerative diseases." (PMID 25071843, 2014). "In addition, the relationship between HDAC6 and the regulation of HSP90 activity is also of interest in the context of neurodegenerative diseases." (PMID 40284012, 2025). "The involvement of HDAC6 in several neurodegenerative diseases is already under discussion, however, the results obtained by modulating HDAC6 activity are not entirely conclusive." (PMID 33041780, 2020). "The roles of the class IIb HDAC6 in preconditioning are not full understood, though HDAC6 is a major regulator of autophagic flux in neurodegenerative diseases and a contributor to pathological responses in the heart." (PMID 26175715, 2015). "With regard to the neurodegenerative disease aspect of TDP-43, we addressed the question if TDP-43 down-regulation might impair neurite outgrowth in a manner involving HDAC6." (PMID 21878116, 2011). "While HDAC6 function during brain development has not been extensively studied, HDAC6 has an important role in the regulation of mechanisms related with different neurodegenerative diseases in adult brain." (PMID 20886111, 2010). "Cells lacking HDAC6 activity are unable to use autophagy to compensate for impaired UPS function, and in a Drosophila model of neurodegenerative disease, HDAC6 was shown to be essential to rescue neurodegeneration caused by UPS failure via autophagy induction." (PMID 26287246, 2015). "In addition, HDAC6-specific inhibitors also used in neurodegenerative disease, the absence of a novel CHIP substrate, HDAC6, has been shown to mitigate the abnormal accumulation of Tau, while the absence of HDAC6 activity further enhances the efficacy of Hsp90 inhibitors, leading to tau degradation." (PMID 34530730, 2021).
infection (50 papers, 2008 to 2026). The state of being infected such as from the introduction of a foreign agent such as serum, vaccine, antigenic substance or organism. "Comparative analysis of wild-type (WT) and HDAC6-deficient (HDAC6-/-) mice in this infection model revealed that HDAC6 deficiency exacerbates disease progression, including significant weight loss, severe pulmonary inflammation, and impaired C." (PMID 41977198, 2026). "We found that both viruses caused significant reduction in HDAC6 mRNA levels in PK15 cells after infection for 12 h at moi = 1 or 18 h at moi = 0.1." (PMID 39861880, 2025). "When specific types of inflammasomes form, an HDAC6-dependent perinuclear puncta of proteins implicated in the cell’s response to infection assembles." (PMID 36056070, 2022). "The treatment with bafilomycin A1 enhances the accumulation of p62 during the infection at the same level in both genotypes, abrogating the deficiency in autophagy observed in Hdac6+/+ BMDCs." (PMID 29281743, 2017). "HDAC6 has also been implicated in the pathogenesis of infections caused by HIV, human T cell leukemia virus, Sendai virus, Influenza A, and other viruses." (PMID 26907353, 2016). "That induction of cPLA2 (loss of mitochondrial function) and HDAC6 (deacetylation of stabilizing MTs) occurs within in the same time frame during infection strongly suggests that both mechanisms cooperate in the structural disintegration of chlamydial compartments." (PMID 28634388, 2017). "Furthermore, HDAC6 has been implicated in regulating the innate immune response during infection, and studies indicate that inhibiting HDAC6 may enhance antiviral immunity." (PMID 40005506, 2025). "The inhibition of HDAC6 interferes with the establishment of infection by blocking the recruitment of the host cell cytoskeleton, which is necessary for the active entry of tachyzoites." (PMID 41533437, 2026). "The immunofluorescence assay showed that HDAC6 aggregates are present in the perinuclear area at 4 h post-infection." (PMID 39747662, 2025). "HDAC6 has been reported to either promote or inhibit the infection process of various viruses by affecting viral life cycle stages and host antiviral response through deacetylation of diverse protein substrates and prevention of protein aggregation." (PMID 39861880, 2025). "Our findings revealed that HDAC6, which had been downregulated following starvation, exhibited upregulation after infection with both types of porcine CoV." (PMID 40938964, 2025). "During infection with Sendai virus, HDAC6 deacetylates β-catenin and enhances its nuclear translocation and promoter binding, acting as a co-activator for IRF3-mediated transcription of type I IFN." (PMID 39861880, 2025). "HDAC6 can either help host cells defend against the virus or be hijacked by the virus to aid its infection." (PMID 39861880, 2025). "In the HDAC6-interactome and acetylome, we also found that HDAC6 significantly interacted with US3 during early infection." (PMID 39747662, 2025). "LC3s or PCNT depletion severely impairs IAV cytoplasm entry and infection, which can be further inhibited by additional silencing of histone deacetylase 6, an APM component." (PMID 40498831, 2025). "In particular, HDAC6 inhibitors can modulate infection by triggering innate immune-mediated bacterial clearance and/or reducing the damage ascribable to the robust inflammation process associated with the infection." (PMID 38371939, 2024). "Later on, HDAC6 isoform gained increasing attention, since its key role in infection was shown, with particular reference to the immune response associated with the infection process." (PMID 38371939, 2024). "Consistently, silencing endogenous TDP-43 significantly decreased HDAC6 levels, increasing the acetylation of the α-tubulin of MTs, which favors the fusogenic and infection activities of HIV-1 Env." (PMID 37685911, 2023).
infection (continued). "HDAC6 functions as a host antiviral factor to prevent the invasion and infection of invaders, while the virus will utilize some HDAC6 properties to escape the host’s defensive response and aid in the virus’s intracellular cycle completion." (PMID 37638049, 2023). "TDP-43 has been reported to determine cell permissivity to HIV-1 fusion and infection acting on tubulin-deacetylase HDAC6." (PMID 37108826, 2023). "These TDP-43 effects on HIV-1-Env-mediated pore fusion formation and infection are exerted through the antiviral factor HDAC6 in a tubulin-deacetylase manner." (PMID 37108826, 2023). "Silencing of endogenous TDP-43 significantly decreased HDAC6 levels and increased the fusogenic and infection activities of the HIV-1 Env." (PMID 35682862, 2022). "Silencing of the endogenous TDP-43 strongly reduces the levels of mRNA and of the HDAC6 enzyme, stabilizing acetylated MTs that favor the infection activity of primary HIV-1 Envs of VNP, progressors and even of non-functional Envs from LTNP-EC individuals." (PMID 36140273, 2022). "In this regard, it has been reported that the ability of the viral Env to trigger signals that overcome the HDAC6 barrier is directly related to its fusion and infection activities." (PMID 35682862, 2022). "Consistently, it has been reported that the ability of the viral Env to trigger signals that overcome the HDAC6 barrier is directly related to its fusion and infection activities." (PMID 36140273, 2022). "This showed that the pro-viral role of HDAC6 ZnF domain during IAV uncoating influenced the infection outcome." (PMID 34359892, 2021). "CA16 infection induced the formation of poly-Ub aggregates, most of which colocalized with SGs and p62 aggregates, and the ubiquitination level of HDAC6 significantly increased in CA16-infected cells." (PMID 32082291, 2020). "The amount of SGs and percentage of cells with SGs were obviously increased in HDAC6 UBD deletion-transfected cells in the presence of CA16 infection but the colocalization of SGs with poly-ubiquitin was significantly inhibited." (PMID 32082291, 2020). "The HDAC6 has been identified as a RIG-I deacetylase, and upon infection with influenza virus (and other RNA viruses, e.g., vesicular stomatitis virus, Sendai virus), the HDAC6-mediated deacetylation of RIG-I activates its RNA virus-sensing function." (PMID 32640546, 2020). "Some interesting data were obtained when analyzing the infection capacity of viral particles obtained over-expressing HDAC6 together with the different Nef mutants." (PMID 31736889, 2019). "In fact, HDAC6 represents a barrier for viral production and infection, as over-expression of HDAC6 promotes Pr55Gag and Vif degradation." (PMID 31736889, 2019). "IAV can utilize the aggresome-processing machinery mediated by HDAC6 to facilitate its uncoating and infection." (PMID 30518648, 2019). "Percent neutrophils in lung lavage fluid post-infection are significantly higher in CF mice, but returned to WT levels with CF/Hdac6 mice." (PMID 31311988, 2019). "Our study is done in the context of CF, which has an inherently different innate immune response and the studies utilize different infections agents, but the impact of HDAC6 on adaptive immunity needs to be further explored." (PMID 31311988, 2019). "HDAC6 appears to limit viral production and infection by promoting the autophagic degradation of Pr55Gag and Vif." (PMID 31736889, 2019). "This manuscript shows that by 14 to 21 days post-infection, the presence of the HDAC6 inhibitor tubistatin A enhances T-cell migration into the lung of infected mice." (PMID 31311988, 2019). "In fact, we observed that Nef-LLAA is unable to target HDAC6 and to neutralize HDAC6-mediated Pr55Gag degradation and inhibition of viral production and infection." (PMID 31736889, 2019).
infection (continued). "Altogether, these results prompted us to suggest that HDAC6 acts as a restriction factor, limiting viral production and infection by driving Pr55Gag and Vif viral proteins to degradation through an aggresome/autophagy route." (PMID 31736889, 2019). "Increasing levels of HDAC6 expression were detected in the Hdac6+/+ DCs as the infection progressed." (PMID 29281743, 2017). "Bacterial entry was similar in Hdac6+/+ and Hdac6-/- DCs at 0 h post-infection (hpi), while bacterial proliferation, measured at 6 hpi, was significantly higher in Hdac6-/- BMDCs for both types of intracellular pathogens, Lm and S. Typhimurium." (PMID 29281743, 2017). "To assess the possible role of HDAC6 in innate immune responses during bacterial pathogenesis, we performed a time-course infection with Lm in granulocyte and monocyte colony-stimulating factor (GM-CSF)-derived BMDCs from Hdac6+/+ and Hdac6-/- mice." (PMID 29281743, 2017). "Results presented here indicate that HDAC6−/− mice are able to deal with UTIs much like their WT counterparts in the hours and days following initiation of infection." (PMID 26907353, 2016). "Quantitative PCR analysis showed that HDAC6 siRNA-1 and-3 infection resulted in the lower mRNA levels in A375.S2 cells compared with negative control (NC) siRNA-treated A375.S2 cells (**P < 0.01 and ***P < 0.001, respectively)." (PMID 25774669, 2015). "In addition, the nuclear HDAC6 was reduced, along with its cytoplasmic accumulation at 4 h post-infection." (PMID 39747662, 2025). "Furthermore, during the early stages of infection, HDAC6 accumulated in the cytoplasm, where it was phosphorylated by the viral protein US3." (PMID 39747662, 2025). "Moreover, we assessed AcTub protein levels as an indicator of HDAC6 functionality and found that infection with porcine CoVs led to a decrease in AcTub levels, consistent with the observed changes in HDAC6 expression." (PMID 40938964, 2025). "Likewise, TDP-43 has been reported to regulate cell permissivity to HIV-1 fusion and infection by acting on HDAC6, thereby modulating the levels of acetylated MTs during early steps of the viral cycle." (PMID 37108826, 2023). "Altogether, these data prompted the suggestion for a new function for TDP-43 in regulating HIV-1 viral production and virion infection efficiency through destabilizing HDAC6 (i.e., mRNA and protein levels) and triggering the autophagic degradation of HIV-1 Vif and Pr55Gag proteins." (PMID 37108826, 2023). "In the regulation of MT dynamics during HIV-1 early infection, the acetylation-deacetylation balance is known to be decisive and carried out by histone deacetylase 6 (HDAC6), an enzyme mainly located in the cytoplasm that regulates the deacetylation of the α-tubulin subunit in MTs." (PMID 37685911, 2023). "Likewise, this anti-HIV-1 HDAC6/TDP-43 axis regulates the infection activity of HIV-1 Envs of the virus isolated from VNP and RP patients down to the levels of the inefficient HIV-1 Envs from viruses of LTNP-EC individuals." (PMID 37685911, 2023). "Furthermore, HDAC6-mediated autophagy is involved in the control of the viral production and virion infection capacity of HIV-1." (PMID 37108826, 2023). "In addition, we carried out an immunoaffinity-based enrichment for acetylated peptides in the BMDCs lysates to ascertain the link between acetylation and the absence or presence of HDAC6 or the infection process." (PMID 36131943, 2022). "The TDP-43/HDAC6 axis could be another factor that is worth exploring in EC individuals that lose the natural control of the infection." (PMID 36140273, 2022). "Therefore, this is the first evidence that a defect of the viral Env from HIV-1+ natural controllers to signal and neutralize the proautophagic factor HDAC6 is related to a defect in infection, virus variability and the LTNP-EC phenotype." (PMID 33995324, 2021).